ALB (albumin)
Diseases named in the same sentence as ALB in open-access papers (continued):
Sharing a sentence is not in itself a finding about the gene and the disease.
tumor (continued). "These, in contrast, are mainly associated with serum proteins such as albumin and tend to localize in tumor vessels." (PMID 31861531, 2019). "Patient HCC025 showed tumor recurrence and active disease at both time points and the mutated peptide was detected in both samples, proving that the tumor synthesized a mutated ALB protein secreted into circulation." (PMID 31039795, 2019). "Alternatively, the secreted protein acidic and rich in cysteine (SPARC) was postulated to sequester albumin in tumor stroma and is partly associated with the tumor-specific uptake of albumin." (PMID 31695779, 2019). "The association between albumin and mortality varied substantially when stratified by cancer stage and tumor resection history." (PMID 31148582, 2019). "Univariate analysis revealed that ALDH2 “GG” genotype, presence of ascites on surgery, microvascular invasion, macrovascular invasion, higher tumor number, larger tumor size, albumin, and AST were significantly associated with shorter overall survival." (PMID 31737110, 2019). "The model indicated that female gender, distal tumor location, higher T-class, and lower serum albumin levels independently associated with decreased blood Hb levels in CRC." (PMID 29348549, 2018). "Postoperative serum albumin level (p < 0.001) and tumor location were both significantly associated with postoperative major wound infection (p = 0.018) in univariate analysis." (PMID 29576961, 2018). "The subgroup analyses indicated that low preoperative serum albumin level is still positively associated with a worse prognosis of UC based on ethnicity, cut-off value, tumor type, analyses type, and sample size." (PMID 29685957, 2018). "It has been theorized that low serum albumin levels are associated with poor nutritional state, increased inflammatory response to the tumor, and increased cytokine release." (PMID 30083224, 2018). "Basically, a decrease in serum albumin is associated with a decrease in important serum proteins of the immune system, which are essential for infection and tumor control." (PMID 29576961, 2018). "In agreement with this notion, it has been investigated that the elevated serum albumin not only is associated with low recurrence rate of HCC in patients but also can inhibit tumor cell proliferation." (PMID 30224923, 2018). "We, therefore, postulated that the increased uptake of IR700DX–maleimide is due to an association with blood proteins, primarily blood serum albumin, via thiols which lead to longer systemic circulation and preferential accumulation in the tumor." (PMID 29313975, 2018). "We conclude that tumor stage, serum albumin and exposure to ART are prognostic factors associated with survival in HIV-positive patients with NHL." (PMID 30083224, 2018). "The present review suggests that the EOC tumor region associated with insufficient supply of O2 and albumin-LCFA complex potentially tends to undergo coagulation factor-dependent inflammatory reactions." (PMID 28417928, 2017). "Nab-paclitaxel, which is created with albumin-bound paclitaxel particles, has high transferability to tumour tissues and hardly cause a hypersensitivity reaction because of different chemical composition compared with docetaxel and paclitaxel." (PMID 29221445, 2017). "Patients with elevated fibrinogen level and decreased albumin levels had 3.00-fold higher risk of tumor progression and had a 3.23-fold higher risk of death compared with those with normal values." (PMID 28548947, 2017). "In univariate survival analysis for BCLC stage B subgroup, DM, albumin, total tumor volume were associated with survival (p< 0.05)." (PMID 28333991, 2017). "Univariate analysis found that ICG-R15, Child-Pugh grade, BCLC staging, TB, INR, Albumin, tumor size, type of resection, transfusion, blood loss, tumor differentiation and high-MVI significantly influenced the OS rate." (PMID 27729623, 2017).
tumor (continued). "In conclusion, tumor size, albumin, PT, AFP levels were independently associated with mortality after ultrasound-guided RFA for HCC, while tumor size, HBV-DNA, AFP levels before treatment, and AFP response were independently associated with recurrence." (PMID 28679433, 2017). "PLR also had a slight association with CEA, CA 19-9, and albumin levels and with tumor cell differentiation." (PMID 27911876, 2017). "Our findings were consistent with previous observations that lower serum ALB increases the risk of tumor progression and poor survival in patients with various cancers." (PMID 29069861, 2017). "Age, gender, albumin level, tumor-associated symptoms, nodal involvement, ratio of metastatic to examined lymph nodes, lymphatic and perineural invasion as well as the administration of postoperative chemotherapy significantly affected the prognosis." (PMID 28288593, 2017). "For this cohort the described association with tumor stage remained significant for BChE and albumin." (PMID 29113384, 2017). "We found that FVC level was associated with gender, age, body mass index (BMI), albumin, tumor size, and tumor stage (P<0.05)." (PMID 28423645, 2017). "LSR was associated with sex (p = 0.023), tumor sizes (p = 0.041), ALB (p = 0.020), ALT (p < 0.001), AST (p = 0.004), CA19-9 (p = 0.008), and CRP (p = 0.025)." (PMID 27294917, 2016). "Multivariate analysis revealed that the factors associated with mortality were serum albumin ≤3.5 g/dL (hazard ratio [HR] 1.459), alpha-fetoprotein >20 ng/mL (HR 1.863), tumor size >3 cm (HR 1.542), BCLC stage A2–A4 (HR 1.488), and treatment modality." (PMID 26512620, 2015). "These are factors that are reflective of patient and tumor characteristics, with β2-microglobulin an indicator of tumor bulk and renal function, and albumin associated with the patient’s general state." (PMID 25624913, 2015). "Considering that PTX has been proved to be a substrate of P-gp, and once injected into the body, Abraxane quickly decomposed into smaller albumin-paclitaxel complexes and enters tumor cells through association with tumor derived SPARC protein." (PMID 26182353, 2015). "Tumour growth led to a reduction in foetal weight associated with decreased serum protein, albumin and glucose levels and low haematocrit in the foetuses of the W group, whereas in the LW foetuses, these changes were less pronounced." (PMID 24383706, 2014). "Tumor responses to albumin-bound paclitaxel have already been linked to SPARC expression in some tumors." (PMID 23895135, 2013). "Univariate analysis showed that increased AFP level, decreased serum albumin level, serosa involvement, and intrahepatic metastasis were closely associated with tumor recurrence after liver resection." (PMID 23618082, 2013). "In this study, we investigated the mechanism underlying the anti-tumor effects of a TIMP-2 fusion protein conjugated with human serum albumin (HSA/TIMP-2)." (PMID 22545131, 2012). "In terms of survival after resection, PCA patients with better nutritional status (measured as having an albumin level greater than 3.5 g/dl), radical resection, early tumor stage and better-differentiated tumors were associated with favorable survival." (PMID 22559838, 2012). "The following parameters were found to be strongly associated with prognosis and prediction value: AFP, albumin level, venous infiltration and the number of tumor nodules." (PMID 19886989, 2009). "All these patients showed a lung shunting below 15% and a tumour-to-normal ratio higher than 2 as determined by diagnostic technetium-99m macroaggregated albumin (Tc-MAA) gamma scintigraphy." (PMID 7947110, 1994). "Significant differences in baseline characteristics were observed across risk groups: low-risk patients exhibited higher Body Mass Index (BMI) and albumin levels, whereas high-risk patients had larger tumor sizes, elevated CRP, Lactate Dehydrogenase (LDH), NLR, and C-PLAN scores." (PMID 41875627, 2026).
tumor (continued). "Building upon our previous use of spatial transcriptomics to evaluate the lipid nanoparticle distribution in 4T1 tumor tissues 24, we adapted this method here to systematically identify cell types and molecular markers linked to the uptake of glycosylated albumin nanoplatforms." (PMID 41355949, 2026). "Studies associated low ALB levels with changes in the tumor microenvironment to more favorable conditions for disease progression and tumor migration, suggesting that serum ALB levels might have a prognostic value for cancer." (PMID 39723668, 2025). "Additionally, the secreted protein acidic and rich in cysteine (SPARC) captures albumin within the tumor stroma, which is associated with tumor-specific albumin uptake." (PMID 41002483, 2025). "In addition, studies have indicated an association between high albumin levels in tumor patients, decreased immune function, and increased mortality." (PMID 39917168, 2025). "Residual tumour and low albumin levels are also associated with poorer survival." (PMID 41228215, 2025). "Tumor removal and weight loss may influence adiponectin levels, leading to reduced inflammation, despite lower albumin levels." (PMID 39652453, 2025). "Additionally, our study found that advanced TNM staging and lower albumin levels were significant risk factors for OS, while tumor multiplicity and higher ECOG performance status scores were linked to worse PFS." (PMID 39996887, 2025). "Cytokines and growth factors released by cancer cells or systemic inflammatory reactions caused by tumours may influence albumin production in the liver." (PMID 40234099, 2025). "Significant associations were also observed between study variables and tumour stage, including serum haemoglobin level (p < 0.001), serum albumin (p = 0.004), neutrophils (p = 0.037), platelets (p < 0.001), PLR (p < 0.001), DNLR (p = 0.038), SII (p < 0.001), PNI (p = 0.005), and age (p = 0.039)." (PMID 40045061, 2025). "Low albumin levels have previously been linked to increased tumor burden and distant metastasis." (PMID 41156248, 2025). "Our findings suggest that albumin may reduce adenocarcinoma risk by preventing DNA damage and inflammatory responses that are critical for tumor initiation and metastasis." (PMID 40719999, 2025). "Despite these limitations, our findings suggest that a high C reactive protein-to-albumin ratio is associated with unfavorable clinicopathological tumor characteristics and that this ratio correlates with established scores, which have been previously assessed in the literature." (PMID 39064483, 2024). "In addition, in a retrospective study of patients with EOC and who were over 75 years old, an albumin level ≤ 3.7 g/dL was associated with a 2.4-times higher risk of residual tumor at cytoreductive surgery." (PMID 38339372, 2024). "Moreover, high levels of CEA (P < .001), TBIL (P = .026), PD-L1 expression (P < .001), and CNLC (P = .024), and low levels of albumin (P = .036) and tumor-infiltrating N1 neutrophils (P = .019) were associated with a shortened OS time." (PMID 38986528, 2024). "Secondly, the metabolic products of the tumor may damage liver function, impairing the liver’s ability to synthesize albumin and thus causing a decrease in albumin levels." (PMID 39687887, 2024). "The results suggest superior accumulation and retention of albumin-bound FHAB within the tumor, whether used alone or when linked to anti-TGFβ, and provided POC for increased immunotherapeutic efficacy of payloads linked to the FHAB." (PMID 39697343, 2024). "Therefore, we recommend that future scoring systems consider incorporating additional factors related to wound healing, such as pre-albumin concentration, underlying vascular disease, tumor size, and the use of intraoperative angiography." (PMID 38418633, 2024).
tumor (continued). "Albumin levels reflect tumor burden and it is a known fact that albumin is associated with the survival of MM.We hypothesized that high tumor burden might be one of the cause of lower levels of albumin and poor chemotherapy response." (PMID 38562177, 2024). "Moreover, around 78 ± 16% of vessels were positive for albumin and total albumin area took up approximately 26.5% of total tumor area (26.5 ± 4.8%), indicating the loss of structural integrity in GBM vasculature." (PMID 39324003, 2024). "Succinctly, the univariable analysis illustrated that the covariates of tumor type and sample size (P < 0.05) significantly affected the pooled effects of ALB, demonstrating that heterogeneity might be caused by these two covariates." (PMID 37566134, 2023). "Low ALB levels may indicate the existence of persistent systemic inflammation and immune system suppression, which are both important mechanisms underlying tumor occurrence and progression." (PMID 37875880, 2023). "The univariate logistic regression revealed that ECOG score (P=0.003), peripheral absolute eosinophil count (AEC) (P=0.013), serum albumin content (P=0.044), body mass index (BMI) (P=0.025), and tumor marker CYFRA21-1 level (P=0.02) were associated with high-grade irAEs." (PMID 36313675, 2022). "Serum albumin is an effective index that reflects the systemic nutritional status of patients with cancer, and poor nutritional status is usually associated with poor tumor prognosis." (PMID 35295561, 2022). "Furthermore, our present study mainly focused on the development of a novel albumin binder-modified radiopharmaceutical, and the mechanism underlying its tumor growth inhibition remains to be further explored." (PMID 35890224, 2022). "The present study aimed to create a carrier system based on albumin, which by binding the CR–Dox complex transports it to the place where the vessels in the tumor are more permeable, and lowering the pH causes aggregation of the carrier and release of the drug." (PMID 35563426, 2022). "A breakthrough in the use of pyridinium salts in vivo was made by Cheng’s team when they created a human serum albumin-facilitated pyridine salt complex that could easily access tumor tissue, had mitochondria-targeting ability, and caused tumor cell apoptosis." (PMID 36559149, 2022). "Serum albumin level could well reflect the nutritional status of cancer patients, and tumor-related inflammatory response may contribute to the loss of albumin." (PMID 35368901, 2022). "But some patients may exist lower ALB levels or be mild malnourished before treatment due to the food-intake disorder, increased tumour-induced protein consumption and a loss of appetite." (PMID 36531036, 2022). "The increased albumin globulin ratio might be explained by suppressed immune function or high and aberrant expression of normal proteins, which were called tumor-associated antigens." (PMID 35814445, 2022). "It was discovered that albumin could serve as a natural means of transporting the nanodrugs to the tumours which might be linked to the increase in the retention and permeation influence." (PMID 34707776, 2021). "Serum albumin (ALB) is not only the most common nutritional indicator; some studies have also found that ALB was associated with the activation of systemic inflammation during tumor proliferation and invasion." (PMID 34568033, 2021). "Furthermore, the ability of endogenous albumin to disseminate into the lymph system has been exploited for T-cell stimulation in tumour-associated lymph nodes." (PMID 33686177, 2021). "Tumor height and albumin were the independent risk factors for iCSF leakage." (PMID 34765541, 2021). "Generally, tumor can directly inhibit the synthesis of ALB by releasing proinflammatory cytokines or make the ALB permeate into interstitial space with the vascular permeability's increase in systemic inflammation response, causing low serum ALB level." (PMID 32089687, 2020).
tumor (continued). "Binding of SPARC to albumin causes release of free drug, which permeates into tumor cells." (PMID 31858848, 2020). "Recent studies from independent groups have shed light on complex signaling pathways involved in the metabolic reprogramming in KRAS-transformed cells, which use macropinocytosis as the primary route for the uptake of large proteins, such as albumin, in a nutrient-deficient tumor microenvironment." (PMID 32807784, 2020). "Univariate analysis revealed that IRE treatment, tumor grade, ALB, and CRP were associated with OS." (PMID 32410380, 2020). "In addition, this scaffold protein was able to delay tumor growth in a mouse model when linked to an anti-tumor antigen-specific single-chain antibody and mouse serum albumin (to extend the half-life of the fusion construct)." (PMID 31921179, 2019). "Notably, substantial difference was found in the association between albumin and mortality when stratifying our analyses in terms of cancer stage and tumor resection status." (PMID 31148582, 2019). "We screened six covariates that significantly affected the matched odds ratio (more than 10%19) of the non‐adjusted model, including age, intraoperative blood loss, tumor stage, postoperative albumin, postoperative serum potassium, and a postoperative opioid analgesic." (PMID 31385451, 2019). "For instance, Liu and coworkers successfully designed a multifunctional dual-responsive HSA-coated MnO2 nanoplatform through albumin-based biomineralization of Mn2+ to overcome tumor hypoxia-associated resistance of PDT, thus can be used for effective combination therapy." (PMID 31526064, 2019). "An ongoing tumor related systemic inflammatory response may also contribute to the progressive loss of albumin." (PMID 30627541, 2018). "The low level of albumin was explained by the protein loss that accompanied advanced tumours." (PMID 30539028, 2018). "The goal of the authors of the scale was to reflect the tumor mass and degree of renal involvement by measuring serum β2-microglobulin concentration and indirectly analyzing bone marrow microenvironment via albumin concentration, which is closely associated with IL-6 concentration." (PMID 29844872, 2018). "In addition to the role in patient nutritional status, peripheral serum albumin level has also been reported to be significantly associated with the host immune system and tumor progression." (PMID 28521783, 2017). "Thus, we surmised that there must be hypoxic tumor areas particularly associated with low albumin levels." (PMID 28417928, 2017). "In addition, gender, tumor stage, albumin, LDH, and ECOG score are also found to be risk factors for death in patients with advanced cancer, which is consistent with data from previous studies." (PMID 28969089, 2017). "This motivates the underlying hypothesis for the current study, namely that the loss of FcRn expression in tumor cells increases the availability of albumin-derived amino acids, thereby promoting tumor growth." (PMID 27974681, 2017). "Although such intervention could relieve the symptoms associated with low circulating albumin concentrations, it may also support tumor growth by contributing to the nutrient pool." (PMID 27974681, 2017). "Additionally, Child-Pugh grade, BCLC staging, Albumin, tumor size, type of resection, blood loss, tumor differentiation and high-MVI affected the RFS rate in the univariate analysis." (PMID 27729623, 2017). "CRP >5 mg/L was associated with advanced tumor stage, lower albumin level, and lower PFSR." (PMID 26799163, 2016). "Albumin was associated with patient age, T status, and tumour size." (PMID 27632196, 2016).